PUS7 (pseudouridine synthase 7)
Diseases named in the same sentence as PUS7 in open-access papers (continued):
Sharing a sentence is not in itself a finding about the gene and the disease.
colon cancer (5 papers, 2023 to 2025). "PUS7 also promotes malignant phenotypes in colon cancer by stimulating the PI3K/AKT/mTOR signalling pathway." (PMID 39834094, 2025). "Ψ fraction change of 7SK for another colon cancer cell line DLD-1 had also shown the similar trend after PUS7 KD." (PMID 41168165, 2025). "MYC was significantly regulated in colon cancer cells with restricted or enhanced expression of PUS7." (PMID 39162904, 2024). "PUS7 is upregulated in colon cancer tissues and closely correlated with poor prognosis." (PMID 41168165, 2025). "While the precise role of PUS7 as a pseudouridylate synthase in promoting colon cancer metastasis remains unclear, current evidence merely suggests that pseudouridylation plays a significant role in promoting tumour malignant phenotypes." (PMID 39834094, 2025). "Furthermore, it is reported that PUS7 can regulate the metastatic ability of colon cancer cells through the HSP90/PUS7/LASP1 axis." (PMID 37420297, 2023). "In ovarian and colon cancers, overexpression of SNORA70E and PUS7, respectively, has been demonstrated to enhance cell propagation, invasion, and migration, thereby facilitating tumour progression." (PMID 39834094, 2025). "For instance, PUS7 overexpression enhances proliferation, invasion, and resistance to apoptosis via the phosphatidylinositol 3‐kinase (PI3K)/AKT/mechanistic target of rapamycin kinase (mTOR) pathway in colon cancer cells." (PMID 39834094, 2025). "In addition, studies have shown that PUS7 can influence colon cancer cell metastasis by regulating LASP1, but does not affect tumor cell proliferation." (PMID 37420297, 2023).
Intellectual disability (5 papers, 2021 to 2026). "Recently, papers reported that variants in PUS7 in 16 patients were involved in marked growth retardation with microcephaly, associated with intellectual disability and behavioral issues such as self-injurious and aggressive behavior." (PMID 42249560, 2026). "Among genes at this locus, PUS7 is associated with intellectual disability and neurological defects." (PMID 34493297, 2021). "Notably, while the role of PUS7 mutations in cancer is largely unexplored, mutations in PUS7 have been reported to cause intellectual disability with growth retardation, accompanied by reduced Ψ13 levels in tRNAs." (PMID 40940790, 2025).
acute myeloid leukemia (4 papers, 2020 to 2025). Acute myeloid leukemia (AML) is a group of neoplasms arising from precursor cells committed to the myeloid cell-line differentiation. "Impaired PUS7 function retards ESC differentiation and promotes malignant transformation to generate aggressive acute myeloid leukemia (AML) stem cells." (PMID 32194861, 2020).
gastric cancer (4 papers, 2024 to 2026). A primary or metastatic malignant neoplasm involving the stomach. "Notably, ALKBH3 functions as a tumor suppressor in gastric cancer, and its expression is closely associated with PUS7 levels in tumor tissues." (PMID 39737343, 2024). "Despite the very different responses to genes in different cancer cells, further validation is needed to explore the specificity of PUS7‐ALKBH3 pseudouridylation axis in gastric cancer." (PMID 39175405, 2024). "Our findings indicate a significant reduction of PUS7 in gastric cancer tissues compared to adjacent non‐tumour tissues." (PMID 39175405, 2024). "To investigate the role of PUS7 in gastric cancer, we examined the protein expression of PUS7 in human gastric tumour tissues from two independent cohorts." (PMID 39175405, 2024). "Functional analyses reveal that PUS7 inhibits gastric cancer cell proliferation and tumour growth via its catalytic activity." (PMID 39175405, 2024). "Immunohistochemistry and Western blotting were used to assess PUS7 protein levels in human gastric cancer tissues." (PMID 39175405, 2024). "Gastric cancer was used as the model in this study to elucidate the role of PUS7‐ALKBH3 pseudouridylation axis in cancer." (PMID 39175405, 2024). "Our investigation has uncovered a compelling mechanism whereby PUS7 mediates mRNA pseudouridylation in the context of gastric cancer progression." (PMID 39175405, 2024). "PUS7 impacts gastric cancer cells by inhibiting their proliferation and tumour growth through its Ψ catalytic activity." (PMID 39175405, 2024). "Since three‐dimensional (3D) cell culture is more biologically relevant to living organisms than two‐dimensional culture, we employed 3D colony formation assays to detect the effect of PUS7 on gastric cancer cell proliferation." (PMID 39175405, 2024). "Taken together, these findings indicate that PUS7 inhibits the proliferation and tumour growth of gastric cancer cells, which is dependent on its catalytic activity." (PMID 39175405, 2024). "While studying the effect of PUS7 on gastric cancer cells, we made the serendipitous observation that knockdown of PUS7 dramatically reduced the expression of the demethylase ALKBH3 in MKN45 cells." (PMID 39175405, 2024). "To determine the function of PUS7 in gastric carcinogenesis, we first detected the level of PUS7 protein in human gastric cancer cell lines." (PMID 39175405, 2024). "Functional analyses demonstrated that PUS7 inhibits gastric cancer cell proliferation and tumor growth through its catalytic activity." (PMID 39737343, 2024). "This study investigates the impact of pseudouridine synthase 7 (PUS7)‐mediated pseudouridylation of Alpha‐ketoglutarate‐dependent Dioxygenase alkB Homolog 3 (ALKBH3) mRNA in gastric cancer." (PMID 39175405, 2024). "The relationship between PUS7 and gastric cancer progression was examined using 3D colony formation assays and subcutaneous xenograft models." (PMID 39175405, 2024). "Future studies are warranted to explore whether PUS7 also participates in regulating tRNA pseudouridylation and assess its impact on the progression of gastric cancer." (PMID 39175405, 2024). "Furthermore, we find that PUS7 inhibits the proliferation and tumour growth of gastric cancer cells in a manner that depends on its catalytic activity." (PMID 39175405, 2024). "Thus, we identify PUS7 and ALKBH3 as novel gastric cancer suppressor genes, and our findings suggest that PUS7‐dependent pseudouridylation of ALKBH3 mRNA inhibits gastric carcinogenesis." (PMID 39175405, 2024). "Importantly, ALKBH3 functions as a tumour suppressor in gastric cancer, with its expression closely correlated with PUS7 levels in tumour tissues." (PMID 39175405, 2024). "However, our data show that PUS7 expression is decreased in human gastric cancer tissues from two independent cohorts by using western blot and immunohistochemistry analyses." (PMID 39175405, 2024).
gastric cancer (continued). "For instance, PUS7-dependent pseudouridylation of ALKBH3 mRNA enhances its translation efficiency, inhibiting gastric cancer cell proliferation and tumor growth." (PMID 40260225, 2025). "PUS7 and ALKBH3 exert an inhibitory effect on the proliferation and tumour growth of gastric cancer cells." (PMID 39175405, 2024). "Our study demonstrates that the expression levels of both PUS7 and ALKBH3 are significantly diminished in gastric cancer tissues." (PMID 39175405, 2024). "Our study sheds new light on this issue by demonstrating that PUS7‐dependent pseudouridylation of ALKBH3 mRNA increases the translation efficiency of ALKBH3 mRNA and subsequently suppresses gastric cancer cell proliferation and tumour growth." (PMID 39175405, 2024). "Here, our study reveals that the expression of PUS7 and ALKBH3 are both significantly reduced in gastric cancer tissues." (PMID 39175405, 2024). "PUS7‐dependent pseudouridylation of ALKBH3 mRNA enhances its translation, thereby suppressing gastric cancer progression." (PMID 39175405, 2024). "The expression levels of PUS7 and ALKBH3 are significantly correlated in gastric tumors, positioning them as potential prognostic indicators and therapeutic targets for patients with gastric cancer." (PMID 39737343, 2024). "More importantly, subcutaneous implantation analysis of gastric cancer cells in nude mice revealed that overexpression of wild‐type PUS7, but not the PUS7‐D294A mutant, significantly suppressed the tumourigenicity of AGS cells." (PMID 39175405, 2024). "Recent findings indicate that PUS7 is significantly downregulated in gastric cancer tissue compared with adjacent nontumor tissue." (PMID 39737343, 2024). "The expression levels of PUS7 and ALKBH3 are significantly correlated in gastric tumours, which may be potential prognostic predictors and therapeutic targets for patients with gastric cancer." (PMID 39175405, 2024). "PUS7 and ALKBH3 are characterized as novel tumour suppressors in gastric cancer." (PMID 39175405, 2024).
breast carcinoma (3 papers, 2022 to 2026). "We further analyzed the correlation of PUS7 with the ribosome biogenesis-related gene set18 in breast cancer patients using the GEPIA2 website and a correlation coeffient (R) of 0.49 was obtained (P < 0.05)." (PMID 41554761, 2026). "A correlation coefficient (R) of 0.38 was revealed between PUS7 expression and the stemness-related gene set in breast cancer patients (P < 0.05)." (PMID 41554761, 2026). "Next, we investigated the relationships between PUS7 expression and differentially expressed genes in breast cancer and TNBC." (PMID 41554761, 2026). "The mRNA levels of key PUS family members, i.e., PUS1, PUS3, PUS4, and PUS7, were significantly higher in breast cancer patient tissues compared with normal breast tissues." (PMID 41554761, 2026). "Because of the recently identified close correlation of ribosome biogenesis and the stemness in TNBC18, we further analyzed the correlation of PUS7 with the stemness-related gene set in breast cancer patients using the GEPIA2 website." (PMID 41554761, 2026). "While higher expression of PUS4 was associated with more favorable prognosis, higher expression of PUS1, PUS3, and PUS7 in breast cancer patients was correlated with poorer prognosis." (PMID 41554761, 2026). "We further investigated the protein level of PUS7 in a panel of breast cancer cell lines." (PMID 41554761, 2026). "High-level correlation between PUS7 and three key stemness-related genes (SMAD2, c-Myc, EpCAM) was further revealed in breast cancer and TNBC patients through TIMER analysis." (PMID 41554761, 2026).
non-small cell lung carcinoma (3 papers, 2023 to 2025). A group of at least three distinct histological types of lung cancer, including non-small cell squamous cell carcinoma, adenocarcinoma, and large cell carcinoma. "Here, we focused on the role and clinical significance of PUS7 in non-small cell lung cancer." (PMID 37420297, 2023).
pancreatic cancer (3 papers, 2024 to 2026). "In contrast, PUS7 overexpression enhanced the migratory and invasive capacity of pancreatic cancer cells while inducing the opposite changes in EMT-associated protein levels." (PMID 40940790, 2025). "The inhibitory effects of S428‐1145 and DNase I on pancreatic cancer are mediated through blocking the PUS7/NETs/M2 macrophage pathway." (PMID 41496500, 2026). "In pancreatic cancer, PUS7 knockdown significantly reduced tumor growth in mouse xenografts and was associated with a decrease in Ki-67–positive proliferating cells within tumor tissues." (PMID 40940790, 2025). "In pancreatic cancer, PUS7 knockdown significantly suppressed the migratory and invasive abilities of pancreatic cancer cells, increased E-cadherin levels, and reduced V-cadherin and Vimentin expression." (PMID 40940790, 2025). "In pancreatic cancer, PUS7 promotes malignant phenotypes through its interaction with anillin (ANLN), thereby activating the MYC signaling pathway." (PMID 40940790, 2025). "Furthermore, our study revealed that high PUS7 expression is markedly associated with poor prognosis, enhanced tumour stemness, and reduced immune infiltration, indicating that PUS7 may drive pancreatic cancer progression through modulation of the immune microenvironment." (PMID 41496500, 2026).
leukemia (2 papers, 2023 to 2025). A malignant (clonal) hematologic disorder, involving hematopoietic stem cells and characterized by the presence of primitive or atypical myeloid or lymphoid cells in the bone marrow and the blood. "MDS patients with low PUS7 expression exhibit a higher risk of leukemia transformation, suggesting the critical role of PUS7 in the pathogenesis of hematological malignancies." (PMID 41446042, 2025). "Meanwhile, PUS7 dysfunction ultimately fosters leukemia development by increasing protein synthesis and impairing stem cell differentiation." (PMID 41446042, 2025).
lung adenocarcinoma (2 papers, 2023). A carcinoma that arises from the lung and is characterized by the presence of malignant glandular epithelial cells. "As is shown in the picture, the expression levels of PUS7 were significantly higher in lung squamous cell carcinomas and lung adenocarcinomas than in normal lung tissue." (PMID 37420297, 2023).
lung carcinoma (2 papers, 2024 to 2025). "In lung cancer (LUAD, LUSC), DKC1, PUS1, PUS3, PUS7, TRUB1, and TRUB2 expression was mostly negatively correlated with immune cell infiltration." (PMID 39162904, 2024).
adenoma (1 paper, 2021). A neoplasm arising from the epithelium. "Importantly, PUS7 was upregulated in the context of high clinical stage CRC; for instance, the PUS7 protein levels were dramatically higher in CRC tissues compared to those in adenoma tissues and neighbouring non-malignant tissues." (PMID 33990203, 2021).
cervical cancer (1 paper, 2025). A primary or metastatic malignant neoplasm involving the cervix. "Additionally, Ψ fraction of 7SK in a cervical cancer cell line HeLa was reduced by 34% after PUS7 KD, indicating that 7SK Ψ250 is a conservative Ψ site installed by PUS7 in different cancer types." (PMID 41168165, 2025).
gastric tumour (1 paper, 2024). "To evaluate the clinical association of PUS7 with ALKBH3 expression, we first examined the levels of ALKBH3 protein in human gastric tumour tissues and their paired non‐tumour tissues." (PMID 39175405, 2024). "In cohort 2, immunoblotting of gastric tumour tissues and their paired non‐tumour tissues confirmed that PUS7 protein levels were also obviously reduced in gastric tumour tissues." (PMID 39175405, 2024). "Collectively, these findings indicate that PUS7 inhibits gastric tumour growth via ALKBH3." (PMID 39175405, 2024). "Furthermore, we carefully analyzed the association of PUS7 and ALKBH3 expression in gastric tumour tissues and found a significant correlation between PUS7 and ALKBH3 levels in gastric tumour tissues in both cohorts." (PMID 39175405, 2024). "Importantly, PUS7 functions as a gastric tumour suppressor gene through its catalytic activity." (PMID 39175405, 2024). "Mechanically, PUS7 modifies ALKBH3 mRNA with Ψ, increasing its translation efficiency and thereby suppressing gastric tumour growth." (PMID 39175405, 2024). "Our study provides compelling evidence that both PUS7 and ALKBH3 are significantly and coordinately reduced in gastric tumour tissues, demonstrating their tumour‐suppressive function in gastric carcinogenesis." (PMID 39175405, 2024). "Crucially, PUS7 modifies ALKBH3 mRNA with pseudouridine (Ψ), enhancing its translation efficiency and consequently suppressing gastric tumour growth." (PMID 39175405, 2024). "Given that PUS7 suppresses gastric tumour growth and pseudouridylates ALKBH3 mRNA, it is reasonable to hypothesize that ALKBH3 may be involved in the regulation of PUS7 in gastric carcinogenesis." (PMID 39175405, 2024). "Mechanistically, PUS7 catalyzes the pseudouridylation of ALKBH3 mRNA on the U696 site to enhance its translation efficiency and increase its protein levels, leading to the suppression of gastric tumour growth." (PMID 39175405, 2024).
kidney tumor (1 paper, 2025). "Of note, the average expression in kidney tumor specimens for PUS7 was 1.4× higher (p < 0.001) than in the non-tumorous kidneys or 1.2× higher for WTAP (p < 0.001), according to data from the GENT2 database." (PMID 40699665, 2025).
neuroblastoma (1 paper, 2025). Neuroblastoma (NB) is the most common solid, extracranial childhood tumor. "Functional assays have shown that targeting PUS7 impair cancer cell proliferation in neuroblastoma models where PUS7 is upregulated." (PMID 40940790, 2025). "In neuroblastoma, for instance, PUS7-mediated pseudouridylation of regulatory mRNAs such as ATF4 enhances the translation of proteins involved in amino acid transport, redox balance, and the integrated stress response." (PMID 40940790, 2025). "In neuroblastoma, PUS7 overexpression markedly accelerated xenograft tumor growth and reduced the survival of tumor-bearing mice." (PMID 40940790, 2025). "In neuroblastoma and lymphoma, MYCN and MYC function as upstream regulators of PUS7, driving its expression and contributing to tumor progression." (PMID 40940790, 2025).
osteosarcoma (1 paper, 2024). A usually aggressive malignant bone-forming mesenchymal neoplasm, predominantly affecting adolescents and young adults. "Most importantly, PUS7 possibly regulates osteosarcoma initiation and progression." (PMID 38819212, 2024).
pancreatic ductal adenocarcinoma (1 paper, 2026). An infiltrating adenocarcinoma that arises from the epithelial cells of the pancreas. "In summary, we elucidated the association between the PUS family and tumour progression, with a particular focus on PUS7 in pancreatic ductal adenocarcinoma PDAC." (PMID 41496500, 2026).
renal carcinoma (1 paper, 2023). A carcinoma arising from the epithelium of the renal parenchyma or the renal pelvis. "According to our findings, the expression of PUS1, PUS7, DKC1 and RPUSD1 is highly expressed in most cancer types, and among those genes, the expression of PUS1, PUS7 and RPUSD1 is markedly upregulated in renal cancers, including KICH, KIRC and KIRP." (PMID 37315299, 2023).
Sepsis (1 paper, 2023). Sepsis is defined as life-threatening organ dysfunction caused by a dysregulated host response to infection. "For instance, genes mediating RNA Ψ modification (TRUB1, TRUB2, PUS1, RPUSD3, RPUSD4, PUS7, RPUSD2) were mainly suppressed in sepsis." (PMID 37701433, 2023).
serous ovarian cancer (1 paper, 2021). "Since mutations in RNA modification genes have been reported to be associated with several types of human cancers, the mutation analysis of PUS7 was performed in cBioPortal, demonstrating the fusion of PUS7 with SRSF Protein Kinase 2 (SRPK2) in serous ovarian cancer." (PMID 34827123, 2021).